JAK2 (Janus kinase 2)
Diseases named in the same sentence as JAK2 in open-access papers (continued):
Sharing a sentence is not in itself a finding about the gene and the disease.
myeloproliferative neoplasm (continued). "This study suggests that ZT55 represents a new class of highly-selective, small-molecule therapeutic agents for the treatment of myeloproliferative neoplasms caused by the activating V617F mutation in JAK2." (PMID 30717771, 2019). "For instance, MC1R polymorphism affects BRAF mutant melanoma, a JAK2 germline polymorphism affects JAK2 V617F mutant myeloproliferative neoplasms, and TACC3 polymorphism affects FGFR3 mutant bladder cancer." (PMID 31369573, 2019). "The objective of this review is to characterize studies on BCR-ABL1-negative chronic myeloproliferative neoplasms and to compare the frequency of JAK2, MPL and CALR mutations in PV, ET and PMF." (PMID 31208359, 2019). "It would have been very interesting to evaluate differences in prevalence of JAK2 mutation and clinical consequences between these two groups, considering the relative high incidence of myeloproliferative neoplasm in the MVT group." (PMID 30756343, 2019). "Constitutive JAK2 signaling is a key feature underlying the pathogenesis of myeloproliferative neoplasms." (PMID 30717771, 2019). "In 2013, two groups reported the discovery of mutations in the CALR gene in Myeloproliferative Neoplasms (MPNs), particularly in 60–80% of JAK2 and MPL unmutated Essential Thrombocythemia (ET) and Primary Myelofibrosis (PMF) patients." (PMID 31332222, 2019). "The hallmark of BCR-ABL1-negative myeloproliferative neoplasms (MPNs) is the presence of a driver mutation in JAK2, CALR, or MPL gene." (PMID 31106152, 2019). "The discovery of JAK2V617F and the demonstration that BCR-ABL-negative myeloproliferative neoplasms (MPNs) are driven by abnormal JAK2 activation have led to advances in diagnostic algorithms, prognosis and ultimately also treatment strategies." (PMID 31346467, 2019). "JAK2 mutation was assessed in 90 patients with myeloproliferative disorders from Kashmir valley, the northern most part of India located at 30,000 ft above sea level." (PMID 31870101, 2019). "JAK2 mutation was assessed in 90 patients with myeloproliferative disorders and 47 leukemic patients." (PMID 31870101, 2019). "It is postulated that JAK2 mutation leads to constitutive activation of the JAK2/STAT signaling pathway in myeloproliferative disorders, which in turn extends the inflammatory response or vice versa." (PMID 31741612, 2019). "Prominent examples include EGFR mutations in lung cancer and JAK2 mutations in myeloproliferative disorders." (PMID 31181801, 2019). "It has recently been discovered that a single-site, clonal, gain-of-function mutation of the tyrosine kinase, JAK2 (JAK2 V617F) is present in myeloid cells from the majority of patients with chronic myeloproliferative disorders (CMDs)." (PMID 31870101, 2019). "JAK2 1849G>T mutation status was analyzed by allele specific polymerase chain reaction (AS-PCR) in 90 samples of patients with myeloproliferative disorders as well as hematological malignancies." (PMID 31870101, 2019). "Discovery of the JAK2 V617F mutation has added a new dimension to the overall understanding of the myeloproliferative disorders." (PMID 31870101, 2019). "Ruxolitinib is a potent and selective JAK1/JAK2 inhibitor, with activity against myeloproliferative neoplasms (MPNs) including those harboring the JAK2V617F mutation." (PMID 29515770, 2018). "The somatic mutation JAK2-V617F is frequently observed in BCR/ABL1-negative myeloproliferative neoplasms (MPNs): 92% in polycythemia vera (PV), 55% in essential thrombocythemia (ET), and 50% in primary myelofibrosis (PMF)." (PMID 29928488, 2018). "It has been reported that primary cells, HEL, SET-2, and UKE-1, derived from myeloproliferative neoplasms (MPNs) patients require mutated Janus kinase 2 (JAK2), responsible for increased growth signaling." (PMID 30719023, 2018). "Polycythemia vera (PV) is a myeloproliferative neoplasm characterized by an abnormal increase in red blood cell mass due to an activating mutation in the Janus kinase 2 (JAK2) gene." (PMID 29804268, 2018).
myeloproliferative neoplasm (continued). "These SNPs are inherited together and are frequently associated with the onset of myeloproliferative neoplasms (MPN) positive for both JAK2 V617 and exon 12 mutations." (PMID 29641446, 2018). "The most common cause of acquired primary erythrocytosis is the myeloproliferative neoplasm (MPN) of polycythemia vera (PV) that is molecularly characterized by the JAK2 p.V617F and exon 12 mutations." (PMID 29682367, 2018). "In myeloproliferative neoplasms the JAK2 and CALR mutations has proven to be immunogenic neo-antigens and thus possible targets for peptide vaccination." (PMID 30327655, 2018). "The oncogenic mutations in JAK2 kinase such as single point mutation (Val617Phe) and JAK2 exon 12 mutations are implicated in both myeloproliferative disorders and myelodysplastic syndromes." (PMID 29455673, 2018). "It has been reported that the JAK2 mutation frequency in ET is about 50% and about 60% in all myeloproliferative disorders (MDs)." (PMID 29732039, 2018). "Most notably, we discovered JAK2 p.V617F somatic mutation, a hallmark of myeloproliferative neoplasms, in 1% (9/932) of the NSCLCs." (PMID 29082853, 2017). "The pathological status of myeloproliferative neoplasms (MPNs) is similar to that of CML because MPNs are also characterized by a very strong driver mutation of JAK2 V617F." (PMID 28452984, 2017). "JAK2 mutations or fusion proteins leading to constitutive activation of JAK2 have been implicated in myeloproliferative neoplasms and AML." (PMID 28420416, 2017). "A point mutation of JAK2 V617F was found in more than 50% of patients with myeloproliferative neoplasms (MPNs)." (PMID 28410228, 2017). "The efficacy of Hsp90 inhibition in JAK2/STAT-driven diseases such as myeloproliferative neoplasms has been previously demonstrated, but linked primarily to increased JAK2 degradation." (PMID 29228628, 2017). "Activating JAK2 mutations in other haematological malignancies, such as myeloproliferative neoplasms, have demonstrated the clinical relevance of this gene and drawn more attention to its potential involvement in T-cell lymphoblastic leukaemia/lymphoma." (PMID 29290986, 2017). "A gain-of-function mutation in the tyrosine kinase JAK2 (JAK2V617F) causes human myeloproliferative neoplasms (MPNs)." (PMID 28620086, 2017). "Gain-of-function JAK2 mutant JAK2V617F is an established oncoprotein associated with myeloproliferative neoplasms (MPNs) polycythemia vera, essential thrombocythemia, and primary myelofibrosis." (PMID 28977839, 2017). "Myeloproliferative neoplasms (MPNs) arise in patients having a gain-of-function mutation in Janus kinase 2 (JAK2) or the myeloproliferative leukaemia protein receptor (MPL)." (PMID 28237966, 2017). "Inhibition of the constitutively activated JAK/STAT pathway in JAK2V617F mutated cells by the JAK1/JAK2 inhibitor ruxolitinib resulted in clinical benefits in patients with myeloproliferative neoplasms." (PMID 29228564, 2017). "In the myeloproliferative disorders, such as polycythemia vera, a somatic activating mutation in the Jak2 kinase resulted in hyperactivation of JAK2 and promoted the development of myeloproliferative disorders." (PMID 28591704, 2017). "Surprisingly, the phenotype of myeloproliferative disorders associated with CALR mutations includes growth factor independent activation of JAK2, and these patients respond to treatment with JAK inhibitors, such as Ruxolitinib." (PMID 29218307, 2017). "The recurrent V617F mutation in JAK2 (JAK2V617F) has emerged as the primary contributor to the pathogenesis of myeloproliferative neoplasms (MPN)." (PMID 26755644, 2016). "CALR mutations are identified in about 30% of JAK2/MPL-unmutated myeloproliferative neoplasms (MPNs) including essential thrombocythemia (ET) and primary myelofibrosis." (PMID 27716741, 2016).
myeloproliferative neoplasm (continued). "For example, a recent novel mutation in the Janus activated kinase 2 gene (JAK2 V617F) seems to be prevalent in patients with mesenteric vein thrombosis and myeloproliferative disorders." (PMID 27607449, 2016). "Mutations in JAK2 have been identified in patients with varies forms of myeloproliferative disorders." (PMID 27551334, 2016). "Among these genes was Janus kinase 2 (JAK2) that is implicated in the progression of myeloproliferative neoplasms." (PMID 26202837, 2015). "In particular, a somatic mutation in the JAK2 protein, V617F, was identified in myeloproliferative neoplasms, including 95% of patients with polycythemia vera and ~50% of patients with essential thrombocythemia and primary myelofibrosis." (PMID 26202837, 2015). "Monitoring of the JAK2 V617F allele burden in myeloproliferative neoplasms after allogeneic stem cell transplantation is useful to determine levels of residual disease and has the potential to detect early relapse and guide subsequent clinical intervention." (PMID 26346984, 2015). "There are contradictory reports about the association between JAK2 mutation and thrombosis in patients with myeloproliferative neoplasm." (PMID 25878908, 2015). "A genome-wide associate study seems to support this, with the identification of a SNP in the JAK2 locus (rs10974944), which predisposed to the development of JAK2 V617F-positive myeloproliferative neoplasm." (PMID 27600067, 2015). "Recent studies have implicated the de-regulation of JAK2 kinase activity in a number of myeloproliferative diseases which is due to chromosomal translocations in hematopoietic tumors and mutations within the pseudokinase domain." (PMID 26202837, 2015). "The gain of function mutation JAK2-V617F is very frequently found in myeloproliferative neoplasms (MPNs) and is strongly implicated in pathogenesis of these and other hematological malignancies." (PMID 24404189, 2014). "Myeloproliferative neoplasms (MPNs) are a group of clonal disorders characterized by hyperproliferation of hematologic cell lines and have been associated with tyrosine kinase JAK2-V617F mutations." (PMID 24744787, 2014). "Additional testing, including PCR or FISH techniques for bcr-abl, JAK-2 mutational testing, erythropoietin levels, and bone marrow examination with cytogenetics, must be warranted for patients suspected of having a myeloproliferative neoplasm." (PMID 25431700, 2014). "For example, detection of the V617F JAK2 mutation is a part of the diagnostic criteria for myeloproliferative neoplasms in the latest version of WHO classification, although consensus is not reached about the detection methods and cut-off levels." (PMID 25310466, 2014). "JAK2 V617F mutation is found in myeloid tumors and in neoplastic proliferation of the hematopoietic cells of myeloproliferative diseases." (PMID 25276445, 2014). "The mutation also made the cells more resistant to JAK2 inhibition with the novel catalytic site JAK2 inhibitor TG101348 now in clinical trial for myeloproliferative neoplasms." (PMID 23861822, 2013). "In 2005, several groups independently reported a valine to phenylalanine substitution mutation at amino acid 617 of Jak2, in a large percentage of myeloproliferative neoplasm (MPN) patients." (PMID 23544085, 2013). "The JAK2 V617F mutation is the most frequent somatic change in myeloproliferative neoplasms, making it an important tumour-specific marker for diagnostic purposes and for the detection of minimal residual disease." (PMID 23617802, 2013). "The acquired mutation (V617F) of Janus kinase 2 (JAK2) is observed in the majority of patients with myeloproliferative neoplasms (MPNs)." (PMID 23300995, 2013).
myeloproliferative neoplasm (continued). "Pathophysiologic findings relevant for myeloproliferative neoplasms are associated with genetic alterations, such as, somatic mutation in the gene that codifies JAK-2 (JAK V617F)." (PMID 24488400, 2013). "Consistent with our results, mutations in the SH2-JH2 linker loop (the exon 12 mutations), similar to V617F, hyperactivate JAK2 and are found in patients with myeloproliferative neoplasms." (PMID 23592968, 2013). "The discovery of a single point mutation in the JAK2 gene in patients with BCR/ABL-negative myeloproliferative neoplasms (MPNs) has not only brought new insights and pathogenesis, but also has made the diagnosis of MPNs much easier." (PMID 23349688, 2013). "Single mutation of JAK2 V617F,which represented constitutive tyrosine kinase activation, was associated with myeloproliferative disorders." (PMID 23704931, 2013). "It is well known that JAK2 mutation occurred in myeloproliferative diseases, such as polycythemia vera (PV), essential thrombocythemia (ET) and primary myelofibrosis (PMF)." (PMID 23469088, 2013). "Polycythemia vera (PV), essential thrombocythemia (ET), and primary myelofibrosis (PMF) are myeloproliferative neoplasms (MPNs) characterized in most cases by a unique somatic mutation, JAK2 V617F." (PMID 22251709, 2012). "Janus kinase 2 gene (JAK2), a specific mediator of erythropoietin signaling, has been implicated in a whole variety of myeloproliferative neoplasms ‐." (PMID 22549126, 2012). "JAK2 gene mutations are known to be very common in polycythemia vera, a myeloproliferative neoplasm characterized by expanded erythropoiesis." (PMID 22844482, 2012). "In particular, JAK2 mutations underlie the myeloproliferative disorders: polycythemia vera, essential thrombocytosis, and primary myelofibrosis." (PMID 22284190, 2012). "JAK2 V617F testing represented an important advance in the diagnostic workup for the recognition of atypical myeloproliferative disease in BCS and PVT patients." (PMID 22909075, 2012). "Literature data pointed out JAK2 V617F mutation is more common in older patients with myeloproliferative disease, as older patients have an higher allele burden." (PMID 22997499, 2012). "Many cases labeled as idiopathic BCS have been subsequently found to be secondary to underlying myeloproliferative disease upon JAK2 V617F testing." (PMID 22480324, 2012). "These explain thrombophilia and increased risk of thrombosis in patients with chronic myeloproliferative disorders, particularly those with JAK2 mutation present." (PMID 21505581, 2011). "Disruption of JH2 domain by constitutive active mutation of Jak2 V617F was discovered recently in human cancers and has a primary role in the pathogenesis of myeloproliferative neoplasms (MPN)." (PMID 21853157, 2011). "The physiological role of the JH2 domain in the regulation of JAK2 activity was highlighted by the discovery of the acquired missense point mutation V617F in myeloproliferative neoplasms (MPN)." (PMID 21533163, 2011). "Essential thrombocytosis, which is one of the conditions of myelo-proliferative disorders, is associated with JAK2 mutation in up to 40% to 50% of cases." (PMID 21569611, 2011). "The JAK2 V617F mutation in exon 14 is the most common mutation in chronic myeloproliferative neoplasms (MPNs); deletion of the entire exon 14 is rarely detected." (PMID 20730051, 2010). "Aberrant JAK2 signaling has been linked to myeloproliferative disorders such as polycythemia vera and chronic myelogenous leukemia." (PMID 20416094, 2010). "A recurrent unique acquired clonal mutation in JAK2 was found in most patients with PV and other myeloproliferative diseases (MPDs)." (PMID 21346910, 2010).
myeloproliferative neoplasm (continued). "Polycythemia vera (PV) is a myeloproliferative neoplasm (MPN) marked by acquisition of an activating mutation of Janus kinase-2 (JAK2), which leads to erythrocytosis and frequently leukocytosis and thrombocytosis, and is associated with a high symptom burden and disease progression." (PMID 40281326, 2025). "A myeloproliferative neoplasm-associated gene panel detected a JAK2 V617F mutation." (PMID 40926892, 2025). "Interestingly, ruxolitinib has previously been shown to elevate glucose levels in myeloproliferative neoplasms, which are clonal disorders of hematopoietic stem cells driven by gain-of-function mutations in e.g., JAK2." (PMID 40702267, 2025). "The JAK2 p.V617F mutation, typically associated with myeloproliferative neoplasms, has been increasingly recognized in solid tumors and may mediate immune evasion, inflammation-driven metastasis, and niche adaptation." (PMID 40842629, 2025). "Despite normal blood counts and unremarkable bone marrow findings, molecular testing confirmed the JAK2 V617F mutation (17% allele frequency), highlighting its critical role in diagnosing occult myeloproliferative neoplasms in patients with unexplained thrombosis." (PMID 40605890, 2025). "Occurrence of a somatic activating mutation valine to phenylalanine (V617F) in the pseudokinase (JH2) domain of JAK2 has been implicated in myeloproliferative neoplasms including polycythemia vera (PV, 90%), essential thrombocythemia (ET, 50%) and primary myelofibrosis (PMF, 50%)." (PMID 38104968, 2024). "A mutation of JAK2 could be detected in splanchnic vein thrombosis and thus provide a marker of latent myeloproliferative neoplasms (MPNs), which are a major primary cause of abdominal vein thrombosis." (PMID 38741148, 2024). "Myeloproliferative neoplasms, polycythemia vera, essential thrombocytosis, and primary myelofibrosis are a unique group of clonal hematopoietic stem cell neoplasms that share somatic, gain-in-function driver mutations in JAK2, CALR, and MPL." (PMID 39598101, 2024). "However, the frequency of the 46/1 haplotype, associated with rs10974944, has been linked to a higher prevalence in patients with myeloproliferative neoplasms, especially those harboring JAK2 V617F+." (PMID 38654055, 2024). "The JAK2 gene, particularly JAK2 V617F mutation, was associated with myeloproliferative neoplasms." (PMID 38886735, 2024). "However, even individuals with a JAK2 V617F mutation burden below 2% should receive medical attention as in time, many of them will develop a myeloproliferative neoplasm indicating the presence of a latent form of Ph-MPN." (PMID 37370982, 2023). "Given that aberrant activation of the JAK2/STAT pathway is linked to the formation of MPNs (Myeloproliferative Neoplasms), which in some cases coincide with high levels of β-catenin activity, a causal connection is tempting to speculate." (PMID 38067194, 2023). "The elevated ATP production could represent a more general feature of the overall metabolic impact of activating JAK2 lesions, as it was previously also observed in JAK2-mutated myeloproliferative neoplasms." (PMID 37637992, 2023). "Considering that the JAK2 V617F mutation is a characteristic gene mutation of myeloproliferative neoplasms, the emergence of the JAK2 V617F mutation might be associated with the appearance of a myeloid phenotype." (PMID 36930401, 2023). "Unlike secondary erythrocytosis, the most common form of primary erythrocytosis is the myeloproliferative neoplasm polycythemia vera (PV) characterized by the presence of the JAK2 V617F somatic mutation in approximately 97% of cases and typically a low serum erythropoietin." (PMID 37123102, 2023). "Interestingly, during our search for cases with JAK2 mutation variants, we came across a case with features of a myeloproliferative neoplasm with thrombocytosis and a JAK2 R564Q (allele variant frequency 43%) point mutation." (PMID 36810551, 2023).